UBE2C (ubiquitin conjugating enzyme E2 C)
Diseases named in the same sentence as UBE2C in open-access papers (continued):
Sharing a sentence is not in itself a finding about the gene and the disease.
ovarian carcinoma (continued). "To verify the relationship between the expression levels and methylation levels of UBE2C in ovarian cancer, we first evaluated UBE2C expression levels in ovarian cancer cell lines (SKOV3 and A2780) and the normal ovarian epithelial cell line IOSE-80." (PMID 35804892, 2022). "Ovarian cancer patients with higher levels of UBE2C expression tended to have shorter OS (log-rank p = 0.00038), lower progression-free survival (PFS; log-rank p = 0.04), and worse post-progression survival (PPS; log-rank p = 0.0017)." (PMID 35804892, 2022). "UBE2C was significantly upregulated in ovarian cancer, and downregulation of UBE2C inhibited cell proliferation, promoted cell apoptosis, induced G2/M cycle arrest, and reversed cisplatin resistance in vivo and in vitro experiments." (PMID 35804892, 2022). "The frequent overexpression of UBE2C was shown in gastric cancer, cervical squamous cell carcinoma, and ovarian cancer." (PMID 35332135, 2022). "In view of the significant hypomethylation of UBE2C in HGSOC from GEO datasets, we theorized that the increased expression of UBE2C in ovarian cancer was probably caused by DNA hypomethylation." (PMID 35804892, 2022). "Research has presented that UBE2C participates in many human malignancies, including ovarian cancer, gastric cancer, and head and neck cell carcinoma." (PMID 36069832, 2022). "As UBE2C was hypomethylated in ovarian cancer, we investigated the methylation status of UBE2C in other cancer types." (PMID 35804892, 2022). "Second, we only verified that inhibiting DNA methylation increases the gene expression of UBE2C in ovarian cancer, ignoring other cancer types." (PMID 35804892, 2022). "Emerging evidence has suggested that UBE2C was highly expressed in various tumors and acted as an oncogene, including ovarian cancer, non-small-cell lung cancer, cervical cancer, head and neck squamous cell carcinoma, etc.." (PMID 36430352, 2022). "A previous study from our group demonstrated that UBE2C was highly expressed in ovarian cancer tissues and promoted ovarian cancer progression by upregulating CDK1." (PMID 35804892, 2022). "Further studies are necessary to verify the prognostic value of CDCA3 and UBE2C and to further understand the role of these genes in ovarian cancer to establish them as potential therapeutic targets." (PMID 34577856, 2021). "Ubiquitin-conjugating enzyme E2 C (UBE2C) is overexpressed in several cancers such as breast, pancreas, colon, prostate, lymphoma and ovarian carcinomas." (PMID 32674429, 2020). "For instance, UBE2C is commonly upregulated in intestinal-type gastric cancer, ovarian cancer, head and neck squamous cell carcinoma, pancreatic ductal adenocarcinoma, HCC, and non-small cell lung cancer." (PMID 32183400, 2020). "Of note, the new potential targets EZH2 and UBE2C were amplified in around 10% and 6% of ovarian cancers, respectively." (PMID 29575713, 2018). "Furthermore, the topmost ranked genes in CR doublets included PRSS1, ECE1 and UBE2C, which promote ovarian cancer chemoresistance and progression." (PMID 40280979, 2025). "The last TAAr is the ubiquitin-conjugating enzyme E2C (UBE2C, gene: UBE2C), which emerges as a pivotal oncogene in ovarian cancer, significantly influencing tumor malignancy and resistance to cisplatin chemotherapy by interacting with Cyclin-Dependent Kinase 1 (CDK1)." (PMID 39033780, 2024). "Downregulation of UBE2C reversed resistance to cisplatin in ovarian cancer cell models." (PMID 37377594, 2023). "Moreover, the IHC staining of UBE2C in ovarian carcinoma tissues obtained from the HPA database also showed that UBE2C was highly expressed in ovarian cancer." (PMID 37803076, 2023). "Knockdown of UBE2C could inhibit the proliferation of ovarian cancer cells and increase apoptosis by blocking the G2/M transition." (PMID 37848988, 2023).
ovarian carcinoma (continued). "Additionally, the results of the previous bioinformatics analysis and bisulfite sequencing PCR clearly indicated the DNA hypomethylation status of UBE2C in ovarian cancer." (PMID 35804892, 2022). "UBE2C was highly expressed in ovarian carcinoma, especially in serous ovarian adenocarcinoma." (PMID 35804892, 2022). "Importantly, our cell experiments also showed that the inhibition of DNA methylation upregulated the expression of UBE2C in ovarian cancer." (PMID 35804892, 2022). "Importantly, we discovered that ovarian cancer cell lines had lower DNA methylation levels of UBE2C than IOSE-80 cells (normal ovarian epithelial cell line) by bisulfite sequencing PCR." (PMID 35804892, 2022). "And depletion of UBE2C reversed the cisplatin resistance in ovarian cancer." (PMID 35332135, 2022). "Importantly, inhibiting DNA methylation was able to restore the expression of UBE2C in ovarian cancer." (PMID 35804892, 2022). "Moreover, the IHC staining of UBE2C in different forms of human cancer obtained from the HPA database also showed that UBE2C protein was upregulated in ovarian cancer and other tumor tissues compared to levels in the corresponding normal tissues." (PMID 35804892, 2022). "UBE2C protein was significantly elevated in breast, colon, and ovarian cancers, and in UCEC." (PMID 34858987, 2021). "Only high expression of UBE2C, TK1, TACC3 and CXCR4 and low expression of MAOB were proved to be associated with poor prognosis of patients with ovarian cancer, suggesting the five genes were considered to be the key genes in ovarian cancer." (PMID 33123295, 2020). "UBE2C is significantly upregulated in several types of cancer including bladder, breast, brain, cervical, esophageal, colorectal, liver, lung, nasopharyngeal, prostate (late-stage), pancreatic, thyroid, stomach, and ovarian cancer." (PMID 30453999, 2018). "Based on GO functional analysis, KEGG pathway analysis, and survival analysis, we found that CDK1, TOP2A, and UBE2C might be the core genes contributing to the development of epithelial ovarian cancer at the molecular level." (PMID 30453999, 2018). "Some of the identified genes such as EZH2 or UBE2C have not been described previously in ovarian cancer but are amplified, linked with detrimental prognosis and potentially druggable, and warrant preclinical and clinical assessment." (PMID 29575713, 2018). "Notably, UBE2C depletion has been reported to reduce platinum resistance in ovarian cancer." (PMID 36131935, 2022). "UBE2Q1 and UBE2C share their molecular function as ubiquitin conjugating enzyme activity with role in protein turnover, which is altered in many cancers but not yet implicated in ovarian cancer." (PMID 33663405, 2021). "Moreover, our meta-analysis identified three specific genes, namely, CDK1, TOP2A and UBE2C, which may be potential targets of ovarian cancer." (PMID 30453999, 2018). "In addition, we found that downregulation of UBE2C could reduce ovarian cancer cell migration." (PMID 35804892, 2022). "It has been shown that knockdown of UBE2C reduced the expression of CDK1 and resulted in inhibition of ovarian cancer malignancy." (PMID 34858987, 2021). "In conclusion, we describe a set of genes overexpressed in ovarian cancer with potential for therapeutic intervention including EZH2 and UBE2C." (PMID 29575713, 2018). "Since a previous study reported that UBE2C could promote DDP resistance in ovarian cancer, cells were treated with different concentrations of DDP (0, 5, 10, 20, 40, and 80 μM) to investigate the effect of UBE2C on GC drug-resistance." (PMID 37840753, 2023). "Taken together, methylation-regulated UBE2C may be a novel biomarker for diagnosis and prognosis, not only for ovarian cancer but a variety of cancers." (PMID 35804892, 2022).
ovarian carcinoma (continued). "UBE2C (Ubiquitin-conjugating enzyme E2C) involved in the modification of abnormal or short-lived proteins by the addition of ubiquitin and lead them toward degradation, a of miRNA-21 negatively correlated with the PTEN target gene, and suppression of miRNA-21inhibits ovarian cancer progression." (PMID 35540695, 2021).
gastric cancer (29 papers, 2017 to 2024). A primary or metastatic malignant neoplasm involving the stomach. "Overexpression of UBE2C is associated with poor prognosis of patients with gastric cancer, and it is also a potential biomarker for intestinal-type gastric cancer." (PMID 39371335, 2024). "In gastric cancer, interfering with UBE2C expression caused the inhibition of cancer cell proliferation, migration, and invasion as well." (PMID 35332135, 2022). "Taken together, we characterized a group of Lauren classification-associated biomarkers, and clarified biological functions of UBE2C, an intestinal-type gastric cancer associated gene." (PMID 30116193, 2018). "For example, UBE2C is highly expressed in gastric cancer, and inhibition of UBE2C expression decreases the development of gastric adenocarcinoma through the Wnt/β-catenin and PI3K/Akt signaling pathways." (PMID 38102624, 2023). "In gastric cancer, patients with higher UBE2C expression levels also had shorter OS (log-rank p = 0.033) and time to first progression(FP; log-rank p < 0.001) but better PPS(log-rank p < 0.001)." (PMID 35804892, 2022). "In gastric cancer, UBE2C overexpression induces chromosomal instability and perturbs the cell cycle." (PMID 33805973, 2021). "UBE2C not only suppresses gastric cancer colony formation, but also inhibits biosynthesis of gastric cancer DNA43." (PMID 34907282, 2021). "UBE2C overexpression has been correlated with poor prognosis in cancers of the stomach, colorectal, thyroid, breast, and pancreas." (PMID 33805973, 2021). "Recent literature has reported that UBE2C plays critical role in the progression of non-small cell lung cancer 8, gastric cancer 9 and breast cancer." (PMID 31942195, 2020). "The protein expression of UBE2C was examined on tissue microarrays from a large cohort of gastric cancer by immunohistochemistry." (PMID 30116193, 2018). "Overexpression of UBE2C accelerates cell cycle progression and promotes cell growth and invasiveness of gastric cancer cells by activating ERK1/2 signaling pathway." (PMID 30116193, 2018). "We comprehensively validated the biological functions of the intestinal-type gastric cancer related gene UBE2C and evaluated its clinical significance on 1,868 cases of gastric cancer tissues from multiple medical centers of Shanghai, China." (PMID 30116193, 2018). "The increased expression of UBE2C of intestinal-type gastric cancer is verified in a large cohort of gastric cancer tissues from Shanghai, China." (PMID 30116193, 2018). "To clarify the underlying molecular mechanisms of UBE2C, we explored the variation of UBE2C gene copy number in gastric cancer cells originated from intestinal-type or diffuse-type gastric cancers." (PMID 30116193, 2018). "UBE2C was negative or weakly positive in normal gastric mucosa, while increased UBE2C expression was seen in gastric cancer, especially the intestinal-type gastric cancer." (PMID 30116193, 2018). "Moreover, increased abundance of securin, CDC20 and UBE2C were shown to be predictors of poor survival in patients with various cancers, including breast, colorectal, and gastric cancers." (PMID 35456956, 2022). "The hypothesis of the amplification of 20q chromosomal region, containing the UBE2C locus, is roughly obvious but is confirmed in studies carried out in colorectal and gastric cancer from microarray datasets and cancer cell lines." (PMID 32192022, 2020). "UBE2C is one of the genes overexpressed in intestinal-type gastric cancer." (PMID 30116193, 2018). "We validated the expression of UBE2C on a separated cohort of gastric cancer from Shanghai, China." (PMID 30116193, 2018). "UBE2C is the gene we found that highly expressed in intestinal-type gastric cancer." (PMID 30116193, 2018). "We reversely verified the functions of UBE2C by enforcing UBE2C expression in gastric cancer cells." (PMID 30116193, 2018). "UBE2C is one of the genes that highly expressed in intestinal-type gastric cancer." (PMID 30116193, 2018).
gastric cancer (continued). "Knockdown of UBE2C resulted in G2/M blockage in intestinal-type gastric cancer cells." (PMID 30116193, 2018). "In gastric cancer, miRNA-17/20 promoted gastric cancer cell growth via targeting UBE2C." (PMID 29021715, 2017). "Similarly, upregulation of UBE2C has been associated with the amplification of copy number in chromosome 20q and activation of MAPK1 signaling, thereby promoting cell growth and invasive abilities of gastric cancer cells." (PMID 39542983, 2024). "In gastric cancer, MYBL2 activated ubiquitin-conjugating enzyme E2 C (UBE2C), leading to cisplatin resistance and cancer progression based on downregulated apoptosis and DNA damage response." (PMID 38835346, 2024). "The univariate and multivariate analyses demonstrate that UBE2C expression, lymphatic metastasis, and TNM staging are independent prognostic indicators in gastric cancer." (PMID 34858987, 2021). "This study established a link between up-regulation of UBE2C with chromosome instability and disturbed ERK signaling pathway in intestinal-type gastric cancer." (PMID 30116193, 2018). "Four out of 5 intestinal-type gastric cancer cell lines BGC-823, MKN-45, MKN-28, and AGS revealed amplification of chromosome 20q which contains the gene locus of UBE2C." (PMID 30116193, 2018). "Two intestinal-type gastric cancer cell lines, BGC-823 which has high expression of UBE2C and SGC-7901 which has low expression of UBE2C, were used to investigate the function of UBE2C on cell growth and invasion." (PMID 30116193, 2018). "In specific, depletion of endogenous UBE2C markedly reduces the level of phosphorylation AURKA via Wnt/β–catenin and PI3K/Akt signaling pathways and then suppressed the growth and metastasis of gastric cancer." (PMID 30914455, 2019). "Ubiquitin-conjugating enzyme E2 C (UBE2C) plays a carcinogenic role in gastric cancer (GC); yet, its role in cisplatin (DDP) resistance in GC is enigmatic." (PMID 37840753, 2023).
hepatocellular carcinoma (29 papers, 2018 to 2026). A malignant tumor that arises from hepatocytes. "In hepatocellular carcinoma, UBE2C upregulation is associated with tumor invasion, dedifferentiation, and poor prognosis." (PMID 37958776, 2023). "Our findings echo a recent study showing that UBE2C expression may be used as a diagnostic biomarker in hepatocellular carcinoma, the most frequent liver cancer in adults." (PMID 37377594, 2023). "The diagnostic value of UBE2C has been previously reported in patients with hepatocellular carcinoma (HCC) and liver cancer." (PMID 38577722, 2024). "First, we reduced the expression of UBE2C and showed that knockdown of UBE2C significantly inhibited the activity of hepatocellular carcinoma cells by CCK8 assay." (PMID 40290433, 2025). "To investigate the relationship between UBE2C and hepatocellular carcinoma migration, we performed a wound healing assay and showed that knockdown of UBE2C significantly inhibited the invasive migration of these cells." (PMID 40290433, 2025). "Considering the importance of UBE2C, we verified its role in hepatocellular carcinoma through a series of in vitro experiments." (PMID 40290433, 2025). "In conclusion, UBE2C enhances the invasive migration of hepatocellular carcinoma cells and correlates with the malignant features of hepatocellular carcinoma." (PMID 40290433, 2025). "The association of UBE2C with RBP7, alongside other upregulated genes such as TK1 and TYMS, underscores its potential role in hepatocellular carcinoma progression and highlights UBE2C as a critical target for therapeutic intervention in this context." (PMID 41301068, 2025). "Specifically in hepatocellular carcinoma, UBE2C is positively correlated with infiltration of regulatory T cells and T follicular helper cells while presenting a negative correlation with macrophage infiltration." (PMID 37958776, 2023). "In hepatocellular carcinoma, UBE2C downregulation increases the sensitivity to chemotherapeutic agents including doxorubicin, 5-fluorouracil (cellular thymidylate synthase inhibitor), and the multikinase inhibitor sorafenib." (PMID 37958776, 2023). "UBE2C is also suggested to be a potential oncogene enhancing migration and invasion in hepatocellular carcinoma." (PMID 37377594, 2023). "Among them, TYMS, KIF2C, UBE2C, and HJURP are associated with unfavorable prognosis in hepatocellular carcinoma, possibly due to the malignant growth of cells." (PMID 37035748, 2023). "Recently, bioinformatics analyses have also discovered a UBE2C overexpression-hypomethylation correlation in hepatocellular carcinoma." (PMID 35804892, 2022). "Another genome-wide DNA methylation analysis in nonalcoholic steatohepatitis-related hepatocellular carcinomas found both hypomethylation of UBE2C promoters and UBE2C upregulation in hepatocellular carcinomas." (PMID 35804892, 2022). "Elevated UBE2C levels have been found in various cancers, including hepatocellular carcinoma (HCC), pancreas, cervical cancer, lung, breast, nasopharyngeal, colorectal, and thyroid cancers." (PMID 34199813, 2021). "For instance, the lower UBE2C expression level indicated higher sensitivity for the therapy of chemotherapeutic drug, including adriamycin and 5-fluorouracil, and knockdown of UBE2C also increased the sensitivity of hepatocellular carcinoma cell to sorafenib." (PMID 34950739, 2021). "UBE2C also modulates migration and invasion in various types of cancers, such as hepatocellular carcinoma, NSCLC, HNSCC and pancreatic ductal adenocarcinoma." (PMID 32899896, 2020). "UBE2C expression is elevated and predicts poor prognosis in hepatocellular carcinoma, esophageal squamous cell carcinoma and intestinal-type gastric cancer." (PMID 32899896, 2020). "UBE2C overexpression has been found in different human cancers, including hepatocellular carcinoma, thyroid, colon, breast, lung, brain, and cervical cancer." (PMID 31067633, 2019).
hepatocellular carcinoma (continued). "In addition, the knockdown of UBE2C significantly attenuated the migration and invasion in hepatocellular carcinoma cells." (PMID 35332135, 2022). "Studies also showed that UBE2C played a crucial role in hepatocellular carcinoma." (PMID 34950739, 2021). "Notably, we identify a predicted pairing between UBE2C and RNF214, two proteins recently implicated in hepatocellular carcinoma separately but through interrelated pathways, suggesting a potential functional link mediated by RNF214-dependent ubiquitination in partnership with UBE2C." (PMID 41726935, 2026). "Nevertheless, UDCA inhibited the expression of cell cycle-related genes and the repression effect was enhanced with a time increase (PLK1, UBE2C, BUB1, CDC20, BIRC5, p <0.001) in hepatoma cell lines SNU387." (PMID 38255993, 2024). "The UBE2C mRNA or protein can hardly be detected in normal tissues; however, it is abnormally elevated in diseases such as cerebral cancer, lung cancer (LC), leukemia, lymphoma, GC, BC, colon cancer (CC) and hepatocellular carcinoma (HCC)." (PMID 33810518, 2021).